AFP (alpha fetoprotein)
Diseases named in the same sentence as AFP in open-access papers (continued):
Sharing a sentence is not in itself a finding about the gene and the disease.
Cirrhosis (continued). "Independent factors included cirrhosis, PVP hypo-enhancement, elevated AFP level (> 40 ng/mL), and lowered albumin level (< 29 g/L) which was similar with that in other studies." (PMID 41105281, 2025). "In MOFA, AFP serum had the highest absolute weight among all features, including genes, while the clinical features HBV status, sex, cirrhosis status, tumour size, and age were deemed the least important." (PMID 40349011, 2025). "In the internal test set, age, sex, AFP, GGT, HBV, and cirrhosis showed significant differences (all p < 0.05)." (PMID 39881111, 2025). "This study utilized three sets of biomarkers, circPanel, AFP, and circPanel plus AFP, to diagnose HBV-HCC, chronic hepatitis B, and HBV-cirrhosis, with a set of healthy controls." (PMID 40584295, 2025). "In the adjusted Cox regression model accounting for gender, race, age at cirrhosis diagnosis, CTP scores, and AFP, the prednisone-exposed group remained independently associated with an increased risk of HCC development (HR: 3.36; P = .040)." (PMID 41142526, 2025). "Based on the univariate logistic regression analyses, the following data were selected for further analysis: gender, BMI, cirrhosis, baseline HBsAg, baseline HBeAg, baseline HBV DNA, ALT, AST, GGT, albumin, AFP, and HGB." (PMID 39702655, 2025). "The features that were retained included age, AFP, HVB, liver failure type, cirrhosis, DBIL, TBIL, CRP, retinol, pre-albumin, platelets, PT, cholinesterase, TT, and monocytes." (PMID 41220690, 2025). "Compared to patients with cirrhosis, those with HCC had higher median values of AFP (31.8 vs. 3.0 ng/mL), AFP-L3 (5.7 vs. 1.2%), and DCP (446.4 vs. 46.6 ng/mL) (p < 0.001 for all)." (PMID 41375033, 2025). "In summary, our findings demonstrate that USP15 is highly expressed in HCC, with levels positively correlated with serum AFP levels, tumor TNM stage, tumor size, cirrhosis, and microvascular invasion, and negatively correlated with patient overall survival." (PMID 39794359, 2025). "After univariate and multivariate logistic regression analysis, the cirrhosis, PVP hypo-enhancement, elevated AFP level (> 40 ng/mL), and lowered albumin level (< 29 g/L) were decided as independent risk factors of MTM-HCC in the training set (all p < 0.05)." (PMID 41105281, 2025). "We performed multidimensional subgroup analyses to verify the prognostic value of the TBA-MLR score among key clinical variables: cirrhosis status, HBV infection, tumor size, microvascular invasion (MVI), and AFP levels." (PMID 40977712, 2025). "In the external test set, age, sex, AFP, GGT, HBV, cirrhosis, and diameter showed significant differences (all p < 0.05)." (PMID 39881111, 2025). "However, AFP has shown limited sensitivity in the clinical detection of early-stage liver cancer, and its levels can also be elevated in conditions such as chronic hepatitis and cirrhosis, which has led to some debate regarding its effectiveness in clinical settings." (PMID 39829957, 2025). "Levels can be elevated in benign liver conditions such as hepatitis and cirrhosis, reducing specificity, while many early stage HCC cases present with normal AFP levels, limiting sensitivity." (PMID 40429981, 2025). "Critical baseline data were analyzed, including age, gender, ALT and AST levels, ALBI, Child-Pugh score, vascular invasion, AFP and PIVKA-II levels, the number and size of tumors in the liver, metastasis, CNLC stage, hepatitis and cirrhosis." (PMID 40071095, 2025). "In the training set, there were significant differences in age, sex, AST, AFP, HBV, cirrhosis, and diameter (all p < 0.05)." (PMID 39881111, 2025). "As indicated, it seemed that patients in DNV group had significantly lower level of alpha-fetoprotein (AFP), lower rates of cirrhosis and decompensated cirrhosis (all P < 0.05)." (PMID 38355447, 2024).
Cirrhosis (continued). "Some scholars have reported that the prognosis of LF patients treated with NBAL is related to cirrhosis, TBIL, INR, infection, HE, Cr, age, MELD score, and AFP, which is generally consistent with our results." (PMID 38545509, 2024). "In patients with cirrhosis and select patients with chronic HBV infection, using ultrasounds on a six-month basis and serum AFP levels is the most accepted screening tool for early diagnosis." (PMID 39410020, 2024). "There was no significantly difference of biochemical indices (ALT, AST, AKP, GGT, TBil, PT and AFP) among CHB, HBV-cirrhosis and HBV-HCC patients, except Alb." (PMID 35347503, 2023). "Significant differences of biochemical indices (ALT, AKP, GGT, TBil, PT and AFP) were identified among CHB, HBV-cirrhosis and HBV-HCC patients, except AST." (PMID 35347503, 2023). "The models included three to seven parameters including age, sex, albumin, total bilirubin, platelets, cirrhosis, liver stiffness measurement, ALT, HBeAg status, diabetes, alcohol abuse, or alpha-fetoprotein." (PMID 37582759, 2023). "When used together with AFP, the AUC increased to 0.931 regarding differentiating early HCC from cirrhosis, which was significantly better than using AFP alone (AUC = 0.712)." (PMID 37763719, 2023). "We designed a pilot study and aimed to investigate the performance of mSEPT9, AFP, PIVKA-II and their combination in hepatic cirrhosis (HC) population." (PMID 37525116, 2023). "High AST and ALT levels in both groups, high GGT levels only in the CHD group, high AFP levels in the CHB group, and low PLT levels in both groups qualified as independent predictors for developing cirrhosis during follow-up." (PMID 38138039, 2023). "Based on the multivariate Cox proportional hazards model of the training group, three variables, including AFP ratio, BCLC stage, and cirrhosis diagnosis, were used to establish satisfactory nomograms for predicting 1-, 3-, and 5-year RFS in HCC patients." (PMID 37124520, 2023). "Patients with CHC and those that achieved SVR but have advanced fibrosis or cirrhosis should undergo regular screening for HCC with ultrasound and alpha-fetoprotein (AFP) assay." (PMID 37048794, 2023). "Although some accepted neoadjuvant therapy patients take the disadvantage for OS with these characters, such as age <65, patients of BCLC B stage, tumor size ≤5 cm, cirrhosis, high-level differentiation, positive MVI, and AFP <400." (PMID 36923427, 2023). "In particular, increased site-specific fucosylation, sialylation and isomeric glycan composition of haptoglobin differentiated better between cirrhosis and early NASH, with further improvements in AUC when combined with AFP compared with AFP alone." (PMID 37920152, 2023). "A meta-analysis suggested combining ultrasound with AFP significantly increases early HCC detection, making it a preferred surveillance strategy for cirrhosis patients until better options are available." (PMID 37711208, 2023). "A binominal logistic regression was performed to ascertain the association of baseline paraclinical data (gender, age, rural/urban origin, cholesterol level, AFP, AST, ALT, GGT, BLBt, Albumin, PT (INR), and PLT levels) with the likelihood to have cirrhosis." (PMID 38138039, 2023). "Tumor size ≥5 cm (P < 0.001), AFP ≥20 ng/L (P < 0.001), ALT ≥40 U/L (P = 0.006), cirrhosis (P = 0.002), and tumor RECIST response (P = 0.008) were independent risk factors of PFS." (PMID 37197414, 2023). "Age and sex were nearly included in all models and other parameters included albumin, total bilirubin, platelets, cirrhosis, liver stiffness measurement, ALT, HBeAg status, diabetes, alcohol abuse, and alpha-fetoprotein." (PMID 37582759, 2023). "Previous studies have shown that the cutoff values of AFP for HCC surveillance are lower in HBV-related cirrhosis patients receiving nucleos(t)ide analogue therapy and HCV-related cirrhosis patients treated with DAAs." (PMID 36831565, 2023).
Cirrhosis (continued). "The model has initially been developed to predict the likelihood of individual patients with cirrhosis having HCC, and we confirm that the score is superior to AFP alone." (PMID 37708457, 2023). "At the same time, there was no statistical difference in other factors (age, gender, BMI, cirrhosis, hepatitis B, ASA score, ALB, PT, PLT, AFP, CEA, CA19-9, CA12-5, anatomical liver resection, the extent of resection, major sizes, multiple tumors)." (PMID 37032348, 2023). "Both the training and validation groups showed that, compared with AFP ratio, BCLC stage, cirrhosis diagnosis, our nomogram provided a better clinical benefit and had significant clinical application in the prediction of HCC recurrence." (PMID 37124520, 2023). "These seven different oxylipins, when combined with AFP, age, and sex, greatly increased the prediction of HBV-related cirrhosis." (PMID 37265499, 2023). "The four groups were statistically different in gender, age, tumor size, MVI, BCLC stage, cirrhosis, albumin, ALT, AFP, NEUT, EO, and LYMPH (P<0.05)." (PMID 36638133, 2023). "Approximately 80% of patients with GHA demonstrate elevated serum AFP levels, which can also be seen in patients with HCC, cirrhosis, and hepatitis; however, normal serum levels have also been reported in patients with GHA." (PMID 37538113, 2023). "Eventually, some personal information, such as age, body mass index (BMI), blood test indicators (AST, GGT, etc.), cirrhosis, BCLC grade, and tumor markers (such as AFP and CEA) were included in the study." (PMID 36980670, 2023). "To this end, we divided patients treated with TACE into subgroups according to their clinical characteristics (age ≤ 50 and >50; tumor size ≤ 5 and >5 cm; AFP > 300 ng/mL; BCLC stage A; cirrhosis; TNM stages I, II, and III)." (PMID 36213835, 2022). "Multivariate regression showed that MVI and AFP were independent predictors of RFS, and tumor length, BCLC stage, HBsAg, and HCV were independent predictors of OS in all rHCC patients with cirrhosis." (PMID 35342424, 2022). "There were contradictory views regarding the contributions of age, gender and cirrhosis to patient survival in HCC, excepting AFP which was an unfavorable factor." (PMID 36685838, 2022). "In this observation, we found that serum AFP levels in HCC patients were significantly higher than in chronic hepatitis B, decompensated hepatic cirrhosis, and hepatitis B virus asymptomatic carrier patients." (PMID 35461226, 2022). "Male gender, age, cirrhosis, HBV genotype C, high direct bilirubin, low albumin, high alpha-fetoprotein, and low platelet count were also identified as significant risk factors for HCC." (PMID 35805045, 2022). "In Taiwan, combined serum AFP levels and ultrasonography have been used for surveillance in patients with chronic HBV and HCV infections in intervals of 3–6 and 6–12 months for cirrhosis and chronic liver disease, respectively." (PMID 36680166, 2022). "The increase of AFP ≥200 IU/mL was around 48.15%, with most of the subjects suffering from HBV infection (59.26%) and cirrhosis background (66.67%)." (PMID 35157721, 2022). "In contrast, a patient with decompensated cirrhosis (INR 2.0, bilirubin 3 mg/dL, moderate ascites), AFP of 400 ng/mL, and 3 cm of viable tumor would have a calculated dropout risk of 17% at 3 months, 32% at 6 months, and 59% at 12 months." (PMID 35029055, 2022). "In patients with cirrhosis, PMCA signal and AFP showed a similar detection capacity for all-stage HCC." (PMID 35388082, 2022). "Advanced age, alcoholism, DM, viral hepatitis and high levels of GGT, AFP and creatinine are also confirmed as predictors of HCC and cirrhosis, while smoking, alcoholism and DM for isolated cirrhosis only." (PMID 35919232, 2022). "However, AFP may also be elevated in some patients with cirrhosis and chronic viral hepatitis." (PMID 36096917, 2022).
Cirrhosis (continued). "AFP is the most widely used for HCC, however, serum AFP levels are related to both HCC and benign liver diseases, such as hepatitis and cirrhosis." (PMID 35365115, 2022). "Here, we review five cases of patients with CHB, cirrhosis, and HCC, and their levels of AFP and the AFP-L3% at various stages of disease including ALT flare, cirrhosis, initial diagnosis of HCC, and recurrence of HCC." (PMID 35458505, 2022). "We randomly selected 10 chronic hepatitis, 10 cirrhosis, and 10 HCC samples to quantify AFP and transaminases." (PMID 36590993, 2022). "Liver enzyme (ALT/AST), cirrhosis, FIB-4, and AFP levels in the BICA and BACA groups were higher than those in the BICI and BACI groups." (PMID 35397497, 2022). "Ultrasound and alpha-fetoprotein (AFP), the most broadly used modalities for HCC surveillance in patients with cirrhosis, lack sensitivity and specificity." (PMID 34299031, 2021). "Based on TCGA dataset, cases with higher age (≥60 years old) and cirrhosis possessed higher ACE2 mRNA expression, while those with poorer vital status – dead, and higher AFP levels (≥400 μg/L) had lower ACE2 mRNA expression." (PMID 34369278, 2021). "Another study suggests that assays of GP73 achieve greater sensitivity and specificity than those for AFP, and GP73 serum levels increase with the malignant potential of liver diseases such as hepatitis, hepatic cirrhosis, and HCC." (PMID 34650031, 2021). "It is also effective (alone or in combination with AFP) in differentiating HCC vs. Hepatitis and HCC vs. Cirrhosis." (PMID 34944400, 2021). "Gender, age, AFP level, condition of virus infection, ALT level, AST level, cirrhosis, and tumor size were unrelated to miR-1246 level (P > 0.05)." (PMID 34163524, 2021). "When comparing cirrhosis vs. early HCC, the isomeric N-glycopeptide Asn207 + 5-6-0-1 better estimated AUC with respect to AFP (AUCAFP = 0.81, and AUCAsn207 + 5-6-0-1 = 0.88, respectively)." (PMID 34436504, 2021). "If the patient has chronic hepatitis or cirrhosis and HCC-suspected lesion with elevated tumor markers such as AFP and AFP-L3, like the present case, the patient would be recommended surgical resection." (PMID 33913027, 2021). "A recent study suggested the utility of a model combining AFP and the FIB-4 model, to predict HCC outcomes for patients with compensated cirrhosis, due to CHB being treated with antiviral therapy." (PMID 34372524, 2021). "Moreover, HAN253WTLTPLK (H5N4S2) and (H5N4S1) of PON1 could be served as potential diagnostic indicators for distinguishing AFP-negative HCC from cirrhosis." (PMID 33889548, 2021). "A significant difference was noticed between HCC patients and the normal healthy group in the following parameters: liver biochemical function parameters, AFP, presence of HCV and of cirrhosis as shown in." (PMID 34582677, 2021). "In contrast, patients with low–medium TBS/low AFP were younger (median age: 60 years (IQR: 67–74), more frequently had a history of cirrhosis (n = 287, 43.8%) and had undergone MIS resection (n = 174, 26.4%) (all p < 0.05)." (PMID 33670174, 2021). "Similar to the BALAD score, the GALAD (gender, age, AFP-L3, AFP and DCP,) model has been used to identify early HCC in patients with nonalcoholic steatohepatitis-related cirrhosis with a sensitivity of 81.4% and specificity of 89.1%." (PMID 34754704, 2021). "ROC curve analysis evidenced the potential of this circRNA in distinguishing patients with hepatitis or cirrhosis from patients with HCC, especially those patients with AFP levels below 200 ng/mL." (PMID 33477833, 2021). "A 68-year-old male with a history of combined kidney/liver transplant for cirrhosis, HCC, and renal failure presented in 2017 with an increasing AFP and an enlarging 2.3 x 1.8 cm celiac lymph node." (PMID 32983688, 2020). "When compared with total AFP, AFP-L3% had a lower AUROC for differentiating cirrhosis from early HCC compared in two case-control studies mainly enrolling non-Hispanic HCV patients." (PMID 32492896, 2020).
Cirrhosis (continued). "The aim of this study was to determine the predictive value of the AFP model for recurrence and survival in a Chinese HBV-related cirrhosis HCC population, and compare the results to the Milan criteria." (PMID 32974380, 2020). "In conclusion, the AFP model performed better than the Milan criteria for predicting recurrence and survival after LT in a Chinese population with HBV-related cirrhosis." (PMID 32974380, 2020). "Previous epidemiologic data show that elevated AFP levels vary from 10% to 43% of people with HCV and compensated cirrhosis, depending mostly on sample size and inclusion criteria." (PMID 32341704, 2020). "This is consistent with others, showing that ALT, AST, AFP, NLR, age, sex, cirrhosis, HBeAg+, and antiviral therapy probably are independent predictors for the development of HBV‐HCC." (PMID 32150664, 2020). "Many previously proposed serum biomarkers for HCC including AFP are elevated, not only in HCC, but also in patients with chronic hepatitis or cirrhosis." (PMID 31968558, 2020). "The expression of NCAPG seemed to differ substantially between some indicated features, including cirrhosis, TNM staging, AFP level." (PMID 32300299, 2020). "The results show that they were indeed related to the indicators of clinical progress and prognosis, such as liver fibrosis/cirrhosis status, MVI, histological grade, and serum AFP." (PMID 31828095, 2019). "AFP distinguished between HCC and healthy subjects with higher accuracy than it did between HCC and cirrhosis, with an AUC of 0.98 (95% CI: 0.96–1.00)." (PMID 31590436, 2019). "In this pilot study, we assessed serum microRNA (miRNA) expression to distinguish cirrhosis and HCC, alone and in combination with the aminotransferase-to-platelet ratio (APRI), Fibrosis 4 (FIB-4), and alpha-fetoprotein (AFP)." (PMID 30781550, 2019). "A study found that levels of lncRNA ZFAS1 are higher in HCC patients than in healthy controls, and in patients with cirrhosis and hepatitis B, and the expression of ZFAS1 is correlated with serum AFP (alpha fetoprotein)." (PMID 31906046, 2019). "The RFS was compared for eleven possible prognostic factors, including gender, age, etiology, presence of cirrhosis, Child-Pugh score, histological grading, CK19/GPC3 sub-typing, tumor diameter, AFP level, macroscopic and microscopic vascular invasion." (PMID 31676847, 2019). "Five predictive models for detecting HCC were developed based on age, gender, AFP, and/or PIVKA-II levels; the best model was validated in an independent cohort of 416 patients with HCC and 412 control subjects with cirrhosis." (PMID 30675135, 2019). "Variables with P < 0.10 related to OS by univariate analysis included hypothyroidism, TSH, cirrhosis status, NLR, AFP, MELD, vascular invasion, tumor diameter, and Milan criteria." (PMID 30453389, 2018). "The other 11 variables were cirrhosis, BCLC C stage, multiple tumor, macrovascular invasion, microvascular invasion, AFP, tumor differentiation, AST/ALT, APRI, Lok index, and King score." (PMID 30057907, 2018). "A combination of S2-bound AGP, AFP and AGP further increased the performance in differentiating between HCC and cirrhosis patients giving an AUROC of 0.86." (PMID 28296934, 2017). "We investigated the association of LASP-1 and its interactors with clinical parameters, including gender, HBV viral status, ALT, main tumour size, multinodular disease, cirrhosis, BCLC staging and AFP, in HBV-related HCC tissues." (PMID 28266596, 2017). "In univariate analysis, the factors associated with RFS included sex, BMI, BCLC stage, tumor number, serum AFP and AST levels, surgical safe margin and histological cirrhosis." (PMID 29176777, 2017). "The mean value of AFP was 5581 ng/ml in patients with HCC compared to 4 and 6 ng/ml in patients with cirrhosis and hepatitis, respectively." (PMID 28296934, 2017).